CYLD (CYLD lysine 63 deubiquitinase)
Diseases named in the same sentence as CYLD in open-access papers (continued):
Sharing a sentence is not in itself a finding about the gene and the disease.
infection (26 papers, 2008 to 2025). The state of being infected such as from the introduction of a foreign agent such as serum, vaccine, antigenic substance or organism. "Infection of Cyld-deficient and wild-type mice with S. aureus confirmed the protective CYLD function." (PMID 39958342, 2025). "During the late stage of infection, CYLD re-associated with the TRAF6/sNASP complex to terminate infection-induced lung inflammation by inhibiting TRAF6 activation." (PMID 40108019, 2025). "In multivariable analysis, only CYLD rs2302759 risk variant was associated with a reduced number of internalized AIEC bacteria at 1 h post-infection within MDM (p = 0.017)." (PMID 31694333, 2019). "Our study reveals a novel function of CYLD in the STING signaling pathway and indicates that CYLD is an important target for modulating the host response to infections caused by DNA pathogens." (PMID 30388174, 2018). "The in vivo data illustrating that Cyld−/− mice have an improved course and control of S. aureus in acute and chronic systemic infection further corroborate that CYLD is a potential therapeutic target to reduce S. aureus colonization and infection." (PMID 39958342, 2025). "Overexpression of CYLD in cells decreased K63-ubiquitination levels, whereas its knock-down increased K63-linked ubiquitination of MYD88 upon infection with NTHi." (PMID 33808506, 2021). "In this context, CYLD was shown to target K63-linked ubiquitin chains on MYD88, which are induced by infection with Haemophilus influenzae (NTHi) in vitro and in vivo." (PMID 33808506, 2021). "This study uncovers an essential function of CYLD in the STING signaling pathway and provides a new perspective for restricting infections caused by DNA pathogens." (PMID 30388174, 2018). "For example, the deubiquitinase A20 and CYLD are induced in response to cytokine treatment and infection and have been found to inhibit NF-кB by hydrolyzing K63-linked polyubiquitin chains on key NF-кB signaling molecules, such as RIP1, TRAF6, and TAK138." (PMID 30348973, 2018). "In this study, we demonstrated a strikingly enhanced CD8+ T cell response following acute blood-stage PbA infection in mice that lack the central regulator CYLD." (PMID 28203236, 2017). "This places CYLD in an attractive position as a therapeutic target molecule in severe infections with Lm and, potentially, other intracellular bacteria." (PMID 26834734, 2015). "No further increase in whole fly AMP levels following systemic infection was observed in mutants of other negative regulators (e.g. CYLD, Nubbin)." (PMID 24586180, 2014). "Upon in vitro infection with Lm, CYLD reduced NF-κB-dependent production of reactive oxygen species, interleukin (IL)-6 secretion, and control of bacteria in macrophages." (PMID 23825949, 2013). "In fact, in vitro infection of IFN-γ-stimulated BMDMs demonstrated that CYLD inhibited activity of NF-κB resulting in reduced IL-6 production, ROS synthesis, and bacterial killing, which were all dependent on NF-κB." (PMID 23825949, 2013). "Infection with Haemophilus influenzae or Eschericia coli induces CYLD expression, which down-regulates the NF-κB inflammatory pathway." (PMID 21455491, 2011). "These opposing effects of CYLD DUB activity in response to different pathogens suggest a potential complexity in targeting host DUBs for therapeutic purposes to combat infection." (PMID 21455491, 2011). "CYLD -/- mice have a hypersensitivity to infection with both Haemophilus influenzae and Eschericia coli." (PMID 21455491, 2011). "However, the evidence is mixed: both the abolition and overexpression of CYLD have resulted in pro- and anti-inflammatory effects in models of cerebral ischemia and infection." (PMID 39945824, 2025). "Of note, infection with S. aureus led to a CYLD-independent and equal activation of MAP kinases including c-Jun-N-terminal kinase (JNK), p38, and ERK in CYLD-competent and CYLD-deficient MDMs." (PMID 39958342, 2025).
infection (continued). "Taken together, we speculated that high/low CYLD expression regulates inflammation and keratinocyte differentiation/proliferation in the various stage from infection-wound healing-tumorigenesis in the middle ear." (PMID 33031450, 2020). "To determine whether the improved parasite control of Cyld−/− mice is mediated by CYLD-deficient CD8+ T cells, we depleted CD8+ T cells in WT and Cyld−/− mice before infection and assessed the survival, vascular leakage, and parasite load." (PMID 28203236, 2017). "Moreover we recently identified an important role for CYLD in modulating host antiviral response by regulating TLR7 expression in mixed infection of bacteria and virus." (PMID 18664270, 2008). "Thus, the underlying infection determines the impact of RIPK2 and CYLD on the outcome of the disease and our identification of a direct inhibition of RIPK2 by CYLD provides a mechanistical explanation of the antagonistic effects of these two signaling molecules." (PMID 26834734, 2015). "This suggests that the regulation of RIPK2 ubiquitination by CYLD (and LUBAC and OTULIN) could influence the response to infection by intracellular bacteria." (PMID 26997266, 2016). "Thus, CYLD impairs the outcome of the infection by inhibiting several non-redundant protective host responses." (PMID 26834734, 2015). "Interestingly, infection with HSV produced diametrically opposite effects in Cyld−/− mice: survival was strongly reduced, and the viral titer was higher both in the spleen and the brain, suggesting that CYLD is essential for the viral response via the STING signaling pathway." (PMID 39945824, 2025). "Regarding DUB expression, no apparent differences were found throughout infection in the levels of HAUSP, also called USP7, UCHL1, A20, USP10, STAMBP, and CYLD." (PMID 36851696, 2023). "Infection by WSN virus, similar to treatment with imiquimod, reduced the level of CYLD but not that of RelB." (PMID 29018444, 2017). "In both sporozoite and asexual blood stage infections, the systemic CD8+ T-cell response was significantly augmented when CYLD was absent." (PMID 28203236, 2017). "Using wildtype and Cyld−/− mice, we show that CYLD significantly reduced pathogen control and production of interferon (IFN)-γ, interleukin (IL)-6, and NOX2 mRNA in liver and spleen resulting in death of wildtype but not of Cyld−/− mice upon high-dose systemic infection." (PMID 23825949, 2013).
neurodegenerative disease (6 papers, 2020 to 2025). A disorder of the central nervous system characterized by gradual and progressive loss of neural tissue and neurologic function. "Although evidence linking CYLD mutations to various neurodegenerative diseases is increasing, basic neurobiological research aimed at understanding the underlying mechanisms is still lacking, hindering the development of therapeutic approaches." (PMID 39945824, 2025). "Thus, the present study identifies and characterizes CYLD substrates, which should provide insights into the molecular mechanisms of synapse organization, function and plasticity, as well as related neurodegenerative diseases." (PMID 36846565, 2023). "In addition to its regulatory function of NF-κB, CYLD is further involved in the regulation of WNT signaling, a signal transduction pathway involved in various CNS functions, such as neurogenesis, tumorigenesis, and the progression of neurodegenerative diseases." (PMID 39945824, 2025).
benign tumor (3 papers, 2013 to 2026). "CYLD is a tumor suppressor gene which is mutated in familial cylindromatosis, a disease characterized by benign tumors of the skin appendage." (PMID 23825949, 2013). "CYLD germline polymorphisms are associated with IBD, while germline mutations in CYLD are responsible for familial cylindromatosis; a disease characterised by benign tumours of the sweat glands around the head, face and neck." (PMID 34269817, 2021).
infectious disease (3 papers, 2013 to 2025). A disorder directly resulting from the presence and activity of a microbial, viral, or parasitic agent in humans. "In addition, it will be important to develop conditional CYLD-deficient mice to decipher the importance of CYLD in individual cell types under infectious disease conditions." (PMID 26834734, 2015). "More specifically, subquinocin, a small molecule inhibitor primarily targeting CYLD, could serve as a potential therapeutic strategy against infectious diseases." (PMID 39958342, 2025).
blood cancers (2 papers, 2023). "Moreover, down-expression of CYLD is known to correlate with several blood cancers." (PMID 37549179, 2023).
hematological malignances (2 papers, 2016 to 2021). "However, most of the previous studies on CYLD regulating the occurrence and development of hematological malignances focused on the CYLD gene mutation or CYLD protein cleavage." (PMID 33827598, 2021).
brain diseases (1 paper, 2025). "Given the wide range of cellular pathways and functions regulated by CYLD, it is not surprising that it has been linked to several brain diseases." (PMID 39945824, 2025).
colon (1 paper, 2016). "We then assessed the role of epithelial CYLD by exposing CYLDΔ932IEC mice to AOM/DSS colon carcinogenesis." (PMID 27561390, 2016).
head and neck tumor (1 paper, 2016). "As the region of head and neck, and the face harbor many stem cell -containing hair follicles in the sebaceous and sweat glands, CYLD genetic aberrations may affect the proliferation control, or inflammatory status of the stem cell niches, thus resulting in predominant head and neck tumor formation." (PMID 31093340, 2016).
hematological cancers (1 paper, 2020). "However, the role and regulation of CYLD in most hematological cancers, including ATLL, has not been well studied." (PMID 32024820, 2020).
inflammation (1 paper, 2018). Aberrant reaction of the microcirculation characterized by movement of fluid and leukocytes from the blood into extravascular tissues. "Via its regulation of NF-κB activation, CYLD may be involved in the pathogenesis of synovial inflammation in RA as well as in the pro-inflammatory effects and hyperproliferation of RA-FLSs." (PMID 30285829, 2018).
CYLD also shares sentences with these, for which no sentence is quoted: skin cancer (5 papers); non-small cell lung carcinoma (4); breast tumor (3); multiple familial trichoepithelioma (3); anal carcinoma (2); autosomal dominant disease (2); basaloid carcinoma of (2); Brooke-Fordyce trichoepitheliomas (2); genetic diseases (2); mantle cell lymphoma (2); non-Hodgkin lymphoma (2); sarcoma (2); T-cell acute lymphoblastic leukemia (2); acute kidney injury (1); adenocarcinoma (1); Alzheimer disease (1); asthma (1); bacterial infection (1); Bazex-Dupre-Christol syndrome (1); Blau syndrome (1); brain tumor (1); cardiac hypertrophy (1); cardiomyopathy (1); colon adenocarcinoma (1); Cowden syndrome (1); cutaneous squamous cell carcinoma (1); embryonal carcinoma (1); endometrial cancer (1); food allergy (1); Gardner syndrome (1).
A further 37 diseases each share a sentence with CYLD in 1 paper.